MYD88 (MYD88 innate immune signal transduction adaptor)
Diseases named in the same sentence as MYD88 in open-access papers (continued):
Sharing a sentence is not in itself a finding about the gene and the disease.
tumor (continued). "Moreover, HJ901 treatment significantly reduced tumor growth in a DLBCL xenograft mouse model with the MyD88 L265P mutation." (PMID 32391356, 2020). "Whether these two neoplasms took place as independent events although coincidentally in time or are originated from a common precursor cell harboring the MYD88 gene mutation cannot be elucidated." (PMID 33180881, 2020). "In addition, tumor-derived exosome-containing heat-shock protein 72 is able to trigger the immunosuppressive function of tumor-associated myeloid cells via the TLR2/MyD88 pathway." (PMID 32788720, 2020). "With the constant accumulation of different gene mutation and expression during tumor differentiation, MyD88 expression might be changing." (PMID 32477927, 2020). "In this study, HJ901, a synthetic ODN containing a sequence with CCT repeats, was found to exhibit a specific inhibitory role in TLR7/9 activation-induced innate immune responses and in reducing cell proliferation and tumor growth in ABC-DLBCL cell lines expressing the MyD88 L265P mutation." (PMID 32391356, 2020). "Furthermore, MyD88 L265P is a tumor-specific mutation, therefore it can elicit T-cell response which can be potentially used in immunotherapy." (PMID 31695691, 2019). "Increased IL-23 may be caused by increased TLR/MyD88 signaling induced by the intestinal microbiota since knockout mice in Myd88−/−and triple knockout mice in Tlr2,4,9−/− display reduced tumor growth." (PMID 30894857, 2019). "Several studies have suggested that the frequency of MYD88 L265P mutation may vary depending on the tumor site or molecular subtype of DLBCL2, 8, 21, 24, 30, 41, but individual studies with different designs hinder clear conclusions." (PMID 28496180, 2017). "Importantly, we found that patients harboring a MYD88 mutation in their tumor cell clone exhibited a significantly shorter DFS as compared to individuals without this genetic abnormality." (PMID 27566587, 2016). "Since WM tumor cells have an overwhelming presence of MYD88[L265P] mutations, they represent an excellent model to test the hypothesis put forth in this article." (PMID 27303665, 2016). "Interestingly, low expression of TLR4 was significantly associated with male patients (p = 0.045); MyD88 expression was related to the tumor site of the colon or rectum (p = 0.034)." (PMID 25547486, 2014). "However, the effect of single MYD88 L265P mutation on tumor growth is confounded by the accumulation of other potential damaging mutations in the same malignant clones." (PMID 25132836, 2014). "MyD88 positive tumours were also associated with a markedly shorter OS." (PMID 24977712, 2014). "In conclusion, MyD88 overexpression was associated with carcinogenesis and tumor progression of EOC and with an increased risk of metastasis and worse survival, and the identification of MyD88 expression as determined by immunohistochemistry is a useful prognostic factor in EOC." (PMID 22533866, 2012). "However, since not all of the tumor cells harbor other genetic changes, it is unknown what makes the difference between a normal cell and a tumor cell when both are MyD88-mutated or, in other words, what makes ‘normal’ cells acquire the tumor phenotype." (PMID 35628381, 2022). "MyD88-deficient mice models have shown MyD88 may either promote or suppress tumor development." (PMID 32477927, 2020). "Fusarium species have been shown to activate the Toll-like receptor 4 (TLR4)/myeloid differentiation primary response 88 (MYD88)/NF-κB signaling pathway in tumor cells, leading to increased expression of microRNA-21 (miR-21)." (PMID 41602751, 2026). "The study presented the enhanced antitumor efficacy against weakly immunogenic tumor antigens by CD8+ T cells engineered with a synthetic CD8α:MyD88 fusion protein." (PMID 40948803, 2025). "Prior research has demonstrated that activating the TLR4/Myd88/NF-κB axis can convert pro-tumor macrophages into tumor-suppressing macrophages, successfully initiating antitumor immune therapy." (PMID 40502627, 2025).
tumor (continued). "Integral to the innate immune response, MyD88's activation is instrumental in driving the synthesis of inflammatory cytokines and modulating the tumor microenvironment by facilitating the infiltration, polarization, and evasion of immune cells." (PMID 39744584, 2025). "In lung cancer, silencing TLR2, TLR4, and TLR9, along with epithelial-specific MyD88/NF-κB signaling, significantly reduces the expression of pro-tumor immunosuppressive factors like RETNLB, while enhancing the expression of anti-tumor cytokines like IFN-γ." (PMID 41200171, 2025). "Activation of the NF-κB and MAPK signaling axes via the MyD88 pathway promotes dendritic cell (DC) maturation and antigen presentation function, laying the foundation for enhancing anti-tumor immune responses." (PMID 41488647, 2025). "In HNSCC cells overexpressing MyD88, there is an upregulation of pro-tumor inflammatory proteins including iNOS, TNF-α, and COX2." (PMID 40560045, 2025). "TRIF domains mediating MyD88-independent signaling provide type I interferon induction and anti-tumor response but require further optimization due to their limited functionality in vivo." (PMID 39941106, 2025). "Extensive studies using GI cancer models have revealed that AMK compounds, especially ATL-1 and ATL-3, inhibit tumor growth through the TLR4/MyD88 pathways and mitochondrial signaling." (PMID 40144663, 2025). "Mutations in the MYD88 and CD79B genes, which play crucial roles in the tumor’s biological framework, are linked to immune privilege and tumor immune evasion." (PMID 40299829, 2025). "Second, TLR4/MyD88 signaling activates the urokinase plasminogen activator system through NF-κB, facilitating tumor invasion and metastasis." (PMID 40703545, 2025). "Toll/IL-1R (TIR) domain proteins, as central signaling hubs in innate immunity, dynamically orchestrate inflammatory responses and immune processes within the tumor microenvironment (TME) by mediating both MyD88-dependent and TRIF-dependent pathways." (PMID 41488647, 2025). "Our investigation also explored the correlation between MyD88 and carcinogenic pathways, revealing its involvement in key signaling cascades that contribute to tumor progression." (PMID 39744584, 2025). "In the context of the tumor microenvironment, the MyD88-dependent pathway exhibits a dual role in immune function." (PMID 41488647, 2025). "Another important TLR, expressed on myeloid cells and neoplastic cells, the TLR2 mediates the recognition of harmful molecules, leading to inflammation and activation of the MyD88/NF‐κB signaling pathway, which promotes tumor cell proliferation and survival." (PMID 40922674, 2025). "Intratumoral microbes upregulate tumor cell PD-L1 expression via LPS-mediated TLR4/MyD88 signaling, reshaping the tumor immune microenvironment, with expression hotspots often corresponding to bacterial aggregation sites." (PMID 40427087, 2025). "A BALB/c-derived xenograft mouse model was established to evaluate the functional role of MyD88 in tumor progression and immunotherapy response." (PMID 40196847, 2025). "Accumulating evidence indicates that the IL-1R/MyD88 signaling axis regulates programmed death-1 (PD-1) expression, thereby sustaining the immunosuppressive activity of TAMs and facilitating tumor progression in melanoma and other malignancies." (PMID 40948759, 2025). "TLR2, through MyD88‐mediated signaling, can activate the NF‐κB pathway, resulting in increased pro‐inflammatory cytokine production, tumor cell proliferation, and survival." (PMID 40922674, 2025). "The complex interactions between TLR4/MyD88 signaling and tumor progression revealed in our study provide important insights into CRC biology and potential prognostic stratification." (PMID 40703545, 2025). "Our study identifies distinct TLR4/MyD88 expression patterns in CRC progression and novel genetic variants associated with aggressive tumor features." (PMID 40703545, 2025).
tumor (continued). "Our findings demonstrate that enhanced TLR4/MyD88 signaling significantly correlates with aggressive tumor features, particularly perineural invasion (p=0.029) and tumor budding (p=0.022)." (PMID 40703545, 2025). "TLR4 signaling operates through both myeloid differentiation factor 88 (MyD88)-dependent and independent pathways, potentially promoting tumor progression by enhancing tumor cell adhesion, invasion, and metastasis via NF-κB regulation." (PMID 40703545, 2025). "A particularly significant finding was the relationship between TLR4/MyD88 activation and patterns of tumor invasion." (PMID 40703545, 2025). "In various solid tumors, such as ovarian, colorectal, and pancreatic cancers, aberrant activation of the MyD88 pathway in tumor-infiltrating myeloid cells leads to excessive production of immunosuppressive cytokines like IL-10 and TGF-β." (PMID 41488647, 2025). "Recent studies have shown that TLR4/MyD88-mediated COX-2/PGE2 signaling in tumor stromal cells promotes cancer progression through multiple mechanisms: inhibiting apoptosis, enhancing angiogenesis, and modulating immune function." (PMID 40703545, 2025). "The progressive increase in MyD88 expression from low-grade (53.8%) through intermediate-grade (70.6%) to high-grade (83.3%) tumor budding supports a dose-response relationship between pathway activation and invasive potential." (PMID 40703545, 2025). "NF-κB activation triggered two distinct pathways that enhanced glycolysis in response to TLR2/MyD88 signaling after tumor-derived exosome ligation." (PMID 40443670, 2025). "HMGB1, a TLR-4 ligand, can induce tumor chemoresistance by activating NF-κB through the TLR4/MyD88 pathway." (PMID 40404908, 2025). "CT had the ability to promote anticancer M1 polarization via the TLR7/MyD88/NF-κB axis as well as induce an anti-tumour CD8+ response (Ref." (PMID 39320855, 2024). "Through the modulation of inflammatory responses and immune reactions, MyD88 orchestrates changes within the tumor immune microenvironment." (PMID 38347830, 2024). "Several studies have shown that MyD88-mediated signal transduction plays a key role in promoting tumor development and progression." (PMID 38785969, 2024). "MyD88 signaling modulates various aspects of cancer progression, including tumor growth, invasion, metabolic reprogramming, and immune evasion." (PMID 39000291, 2024). "Myeloid differentiation factor 88 (MyD88) is crucial for innate immunity, and activation of MyD88 promotes the production of inflammatory cytokines and induces infiltration, polarization, and immune escape of immune cells in the tumor microenvironment." (PMID 38785969, 2024). "In the MDSC-mediated tumor immune microenvironment, inhibition of MyD88 not only directly inhibits the differentiation of MDSCs but also indirectly inhibits MDSC expansion by reducing the secretion of cytokines." (PMID 38785969, 2024). "It upregulates cytokines like IL-6 and TNF-α and downregulates miRNA18a via the TLR-4/MYD88 pathway, further supporting tumor growth and immune evasion." (PMID 39273009, 2024). "The MyD88 protein exerts a profound influence on cancer cell tumorigenesis and the initiation of tumor growth." (PMID 38347830, 2024). "MyD88-induced CYLD in CD11b+ DCs functions as a tumor suppressor in PA via the regulation of DC maturation and function through the NF-κB signaling pathway." (PMID 38825642, 2024). "Analysis of MyD88/TRIF knockout mice with nuclear ATF6 expression in intestinal epithelial cells (nATF6IEC) showed that tumor development was dependent on the activation of STAT3 through MyD88/TRIF signaling." (PMID 38903520, 2024). "MYD88 L265P and CD79B Y196 mutations were detected in 9/14 (64%) and 2/13 (15%) tumor biopsies, respectively." (PMID 38566053, 2024). "Analysis of MyD88 expression showed a statistically significant increase of MyD88 expression levels in tumor-bearing group compared to control group (p < 0.05)." (PMID 39394174, 2024).
tumor (continued). "As a supplementary mechanism, TgPLP stimulates MyD88 signaling pathway during autologous whole‐tumor‐cell vaccine therapy." (PMID 38109851, 2024). "Research has shown that specific gut bacteria such as Fusobacterium nucleatum engage immune signaling pathways, including NF-κB, via TLR/MyD88 signaling in tumor-infiltrating immune cells." (PMID 39273009, 2024). "Depletion of MyD88 in MCF-7 cells markedly inhibits tumor growth in nude mice, with tumor volumes generated from MyD88-deficient MCF-7 cells approximately half the size of those from control cells." (PMID 38347830, 2024). "Our examination of CD36 and MYD88 as therapeutic targets reveals a compelling avenue for personalised tumour therapy." (PMID 38742843, 2024). "In MDA-MB-231 cells, the downregulation of MyD88 influences NF-κB nuclear translocation, resulting in a diminished invasion capacity of tumor cells." (PMID 38347830, 2024). "The multifaceted influence of MyD88 on the tumor immune microenvironment involves the orchestration of multiple cytokines and intricate signaling pathways." (PMID 38347830, 2024). "In conclusion, through wet experiments validation, we demonstrate that CD36 and MYD88 promote tumour proliferation, invasion, and migration in OS." (PMID 38742843, 2024). "In the current study, we revealed that MYD88 is upregulated in tumor tissues and that high expression levels of MYD88 correlate with poor prognosis in PDAC." (PMID 39065761, 2024). "Activation of MyD88 intricately correlates with self-renewal, cytokine production and secretion, as well as expansion of tumor stem cells, thereby influencing tumor development and progression." (PMID 38347830, 2024). "Taken together, the in vitro response to BCG, TME modulation, and tumor remission promoted by BCG in MB49 tumors are intrinsically dependent on MyD88 signaling." (PMID 38835781, 2024). "Tumor-bearing group when treated with WFA showed a statistically significant reduction in MyD88 expression levels compared to the tumor-bearing group (p < 0.01)." (PMID 39394174, 2024). "Altogether, SNLP‐1 can enhance immune activity and play an anti‐tumor role by regulating the TLR4‐mediated MyD88‐dependent signaling pathway." (PMID 39155844, 2024). "Further, the activation of ERK has been shown to drive tumor formation in ApcMin/+ mice by the Toll-like receptor adaptor protein myeloid differentiation factor 88 (MyD88)." (PMID 38277448, 2024). "Activation of the MyD88 pathway promotes tumor formation, while MyD88 knockdown results in reduced clonogenicity in primary ERneg tumors." (PMID 38347830, 2024). "MYD88, involved in the Toll-like receptor signaling pathway, is commonly mutated in PCNSL and has been detected in both tumor tissue and CSF, potentially reflecting the CNS-specific immune response to the tumor." (PMID 39144147, 2024). "Our findings demonstrate that the MyD88-dependent maturation of TiDCs (including cDCs and pDCs) coupled with their migration to dLNs, plays a central role in the induction of tumor-specific immunity as elicited by the intratumoral administration of LTX-315." (PMID 38545099, 2024). "A more profound understanding of the mechanisms through which MyD88 influences BCSCs holds the potential for the development of targeted therapies against these aggressive tumor-initiating cells." (PMID 38347830, 2024). "MyD88 primarily exerts intricate effects on tumor progression through pathways such as Phosphoinositide 3-kinases/Protein kinase B (PI3K/Akt), Toll-like Receptor/Nuclear Factor Kappa B (TLR/NF-κB), and others." (PMID 38347830, 2024). "Several recent studies have demonstrated the key role of MyD88 signaling in promoting tumor metastasis and invasion." (PMID 38785969, 2024).
tumor (continued). "In mouse models, we show that Co-STARs mediate more robust T-cell expansion and more durable tumor regressions than TCRs similarly modified with MyD88 and CD40 co-stimulation." (PMID 38985855, 2024). "These LATS1/2-null tumor cells induced type I interferon production by releasing EVs and activating the TLRs-MYD88/TRIF pathway, thereby potentiating tumor immunogenicity and effectively suppressing melanoma growth." (PMID 39174509, 2024). "Mechanistically, in chimeric and conditionally targeted PDAC mouse models, myeloid-specific TLR4 signaling executes the MyD88-independent TRIF pathway to promote tumor growth, whereas MyD88-dependent signaling inhibits tumor growth." (PMID 38390872, 2024). "Global deletion of type I IFN receptor (IFNAR) or MyD88 (an adaptor molecule that operates downstream of IL-1 receptor and Toll-like receptors) also diminished tumor resistance conferred by Gc-/- FT." (PMID 38662827, 2024). "In that study, using the azoxymethane/dextran sodium sulphate (AOM/DSS) model of CAC which mirrors inflammatory bowel disease-associated CRC in humans, MDSCs were found to be expanded in tumour-bearing mice in a MyD88-dependent manner." (PMID 38464388, 2024). "Consistent with a previous report, LTX-315 strongly inhibited tumor growth in WT mice, an effect that was partially lost in MyD88-/- mice, suggesting that MyD88 is involved in the therapeutic effects of LTX-315." (PMID 38545099, 2024). "But paradoxically, autophagy regulation mediated by the TLR/MyD88 pathway can promote tumor metastasis." (PMID 38523155, 2024). "We evaluated the expression level of MYD88 in 179 primary tumor tissues and 171 normal tissues from the TCGA database." (PMID 39065761, 2024). "TLR2, an upstream signaling molecule of MyD88, depletion impedes the tumor-initiating capacity of cells." (PMID 38347830, 2024). "The ability of tumor secretions to induce ARG1 is completely lost in neutrophils isolated from mice with TLR2 or MyD88 knockouts." (PMID 38523155, 2024). "Using bone marrow radiation chimeras, MyD88 expression in the hematopoietic compartment was found to be necessary and sufficient for enhanced tumor control." (PMID 38662827, 2024). "This treatment activates the MyD88 signaling axis in macrophages and T cells, leading to increased infiltration of cytotoxic T cells and increased tumor inflammation." (PMID 38785969, 2024). "We also co-cultured infected B16-F10 with spleen cells isolated from tumor-bearing WT or MyD88-/- animals previously treated with BCG or untreated." (PMID 38835781, 2024). "Stratified survival curves based on the expression of CD36 and MYD88 were plotted for these tumours." (PMID 38742843, 2024). "In the MYD88-mutant patient-derived xenograft model, KT-413 also showed strong tumor growth inhibition." (PMID 39169396, 2024). "Exosomes released by tumor cells can activate the TLR/MyD88/NF-κB signaling pathway in macrophages, prompting the release of pro-inflammatory cytokines (such as IL-6, TNF-α, GCSF, and CCL2)." (PMID 38347830, 2024). "High MyD88 expression correlates intimately with clinical parameters like tumor size, lymph node metastasis status, and histological grade." (PMID 38347830, 2024). "miR-7-5p targets myeloid differentiation factor 88 (MyD88) to dampen tumor cell proliferation, migration, and invasion of iCCA cells in vitro, thus acting as a tumor suppressor." (PMID 39682684, 2024). "For example, TgPLP can increase the level of antigen-presenting cell markers in bone marrow-derived macrophages by activating the MyD88 pathway, resulting in increasing the production of IL-12 and promoting their phagocytosis of tumor cells." (PMID 38654350, 2024). "Immunotherapy with BCG was not able to induce the recruitment of inflammatory cells in the TME from MyD88-/- mice, impairing tumor control and IFN-γ production by T cells." (PMID 38835781, 2024).